H19 (H19 imprinted maternally expressed transcript)
Diseases named in the same sentence as H19 in open-access papers (continued):
Sharing a sentence is not in itself a finding about the gene and the disease.
glioma (continued). "In a VEGF-A-dependent way, lncRNA H19 interacts with miR-29a to promote glioma progression via angiogenesis (cell proliferation and invasion)." (PMID 37245177, 2023). "The neovascularization of gliomas is facilitated by an interaction between the lncRNA H19 and microRNA-140." (PMID 37245177, 2023). "Multivariate Cox regression analysis of the prognostic performances of differentially expressed lncRNAs identified H19 and plasmacytoma variant translocation 1 (PVT1) as risky lncRNAs and highly accelerated region 1A (HAR1A) as a protective lncRNA in glioma." (PMID 36819921, 2023). "Regression of gliomas and suppression of angiogenesis can be achieved by knocking down the lncRNA H19." (PMID 37245177, 2023). "Acting as a sponge for mir138, which targets HIF1α, lncRNA H19 promotes glioma angiogenesis in a HIF1α- and vascular endothelial growth factor (VEGF)-dependent manner." (PMID 36835628, 2023). "At the molecular level, in addition to the well-established mechanism relying on the O2-deprivation-dependent induction of HIF1α, it has been recently established that, upstream of HIF1α, lncRNA H19 regulates glioma angiogenesis." (PMID 36835628, 2023). "LncRNA H19 promotes angiogenesis in gliomas by increasing the expressions of hypoxia inducible factor 1 subunit alpha (HIF-1α) and vascular endothelial growth factor (VEGF) through targeting miR-138." (PMID 36819921, 2023). "Emerging data are shining light on H19 lncRNA in glioma, which, similarly to LIN28A/B, works by suppressing let-7 to derepress let-7 targets." (PMID 37370851, 2023). "H19 is highly expressed in IDH-mutant gliomas and involved in TMZ resistance by regulating multidrug resistance genes, and its levels are elevated in TMZ-resistant glioma cells." (PMID 36819921, 2023). "The regulation of mTOR signaling was found to be the mechanism by which H19 promotes the proliferation, migration, and autophagy of adult glioma cells." (PMID 37444408, 2023). "For example, MALAT1, HOTAIR, and H19 have been found to promote glioma cell proliferation, migration, invasion, and angiogenesis, thereby acting as oncogenes." (PMID 37444408, 2023). "LncRNA H19, for instance, has been shown to play a role in the epigenetic silencing of tumor suppressor genes in pediatric gliomas." (PMID 37444408, 2023). "H19 increases the proliferation of gastric cancer and glioma cells by sponging miR-141, miR 22-3p, and miR-152 expression." (PMID 37190145, 2023). "In glioma, H19 can also target miR-342 and upregulate the Wnt5a/β-catenin pathway to promote cell proliferation and migration." (PMID 36819921, 2023). "Knockdown of lncRNA H19 inhibited glioma-induced endothelial cell proliferation, migration, and tube formation in vitro." (PMID 37602326, 2023). "Similar study in other temozolomide resistant glioma cells shows that H19 can confer temozolomide resistance by modulating MGMT expression." (PMID 36246634, 2022). "Similar to resistance from TMZ treatment, H19 is upregulated by CREB1 protein under radiotherapy treatment against glioma." (PMID 35955440, 2022). "LncRNA FEZF1-AS1 and lncRNA H19 are up-regulated in glioma tissues and are closely related to glioma progression." (PMID 34937497, 2022). "H19 silence suppressed the proliferation, migration, and angiogenesis of glioma cells by modulating miR-138." (PMID 36046633, 2022). "H19 lncRNA has been shown to promote the proliferation, migration and invasion of glioma cells through targeting of miR-200a." (PMID 35402278, 2022). "Functional assays have proven that H19 was involved in the cell cycle arrest, apoptosis, and DNA synthesis to modulate the radiation response of glioma cells and influenced their radioresistance." (PMID 35955440, 2022). "Lowering H19 or increasing miR-152 can inhibit the proliferation and invasion of glioma cells to inhibit the growth of glioma cells." (PMID 35345660, 2022). "Up-regulation of H19 expression promotes the proliferation, migration, invasion, and angiogenesis of glioma cells." (PMID 35359381, 2022).
glioma (continued). "In glioma cell models, H19 levels are induced by oxidative stress and are increased in U251 and LN229 cells." (PMID 35782387, 2022). "As reported, the over-expression of H19 can promote temozolomide (TMZ) resistance in glioma cell lines." (PMID 36246634, 2022). "Overexpressing H19 in gliomas can contribute to malignant transformation, promote tumor proliferation, invasion, infiltration, and chemoresistance." (PMID 35782387, 2022). "In comparison with normal control, the expression of miR-200a was remarkably reduced in glioma samples, where the RNA levels of H19 and miR-200a were inversely correlated according to Spearman’s correlation analysis." (PMID 34796112, 2021). "The expression of H19 was higher in glioma tissue (low and high grade) and cell lines, including U251 and U87MG cells." (PMID 34322395, 2021). "In summary, the regulatory roles of H19 in glioma have been revealed, which provides novel insights on the therapeutic development by inhibiting the migration and invasion of glioma cells." (PMID 34796112, 2021). "Bioinformatic analyses of clinical datasets were used to measure the expression of H19 lncRNA in paediatric high-grade gliomas (pedHGGs)." (PMID 34502082, 2021). "Angiogenesis: H19 plays a key role in angiogenesis in glioma via several mechanisms, including inhibiting miR-29a and miR-138." (PMID 34322395, 2021). "H19 is overexpressed in glioma tissues, negatively correlates with patient survival, and promotes tumor growth by silencing relevant microRNAs." (PMID 34899682, 2021). "Apart from these, H19 has the potential to act as a biomarker for the prediction of glioma patients' radiosensitivity." (PMID 34159190, 2021). "Previous studies reported that there is a positive correlation between the high expression of H19 and the poor prognosis in glioma patients." (PMID 34159190, 2021). "Recent bioinformatics analysis has shown that H19 can be used as an independent posterior factor of low-grade glioma." (PMID 34199840, 2021). "H19 knockdown inhibited glioma cell proliferation, invasion, and migration, arrested the glioma cell cycle and induced glioma cell apoptosis." (PMID 34977037, 2021). "Knockdown of H19 was able to suppress the proliferation, invasion and migration of glioma cells, which were abolished by the treatment with miR-200a inhibitors." (PMID 34796112, 2021). "H19 was reported to be upregulated in high-grade glioma and facilitated the proliferation of diffuse intrinsic pontine glioma." (PMID 34950662, 2021). "Collectively, these results suggested a strong correlation between H19 level and the radioresistance of glioma." (PMID 34159190, 2021). "H19 silencing reversed glioma cell growth and metastasis by regulating the miR-342-mediated Wnt5a/β-Catenin signaling pathway with decreased levels of vascular endothelial growth factor A (VEGFA), MMP9, Wnt5a, and β-catenin." (PMID 34977037, 2021). "What’s more, H19 was also found to be significantly overexpressed in glioma cells, and its expression increased with the degree of malignancy." (PMID 34796112, 2021). "We suppose that the radioresistance of glioma cells is determined not only by H19 but also by the entire genetic background, but the significant role of H19 cannot be denied." (PMID 34159190, 2021). "As a novel oncogenic factor, up-regulation of H19 was able to promote the proliferation of glioma cells by targeting miR-200a." (PMID 34796112, 2021). "MALAT1, NEAT1, and H19 are among lncRNAs that affect the response of glioma/glioblastoma to chemotherapy." (PMID 34178658, 2021). "H19 silencing has been shown to enhance TMZ cytotoxicity in glioma cells through inhibiting epithelial-mesenchymal transition (EMT) via the Wnt/β-catenin pathway and inactivating NF-kB signaling." (PMID 34178658, 2021). "Consistent with these previous studies, the results of our study revealed H19 expression was remarkably elevated in glioma." (PMID 34796112, 2021).
glioma (continued). "H19 played a vital role in TMZ-resistance in glioma by altering the expression of drug resistance genes such as MRP, MDR, and ABCG2." (PMID 34421359, 2021). "Conversely, downregulation of H19 suppresses glioma cell progression, including, migration, invasion, and proliferation via suppressing the Wnt/β-catenin signaling pathway." (PMID 33980320, 2021). "They found that H19 knock-down suppressed angiogenesis, proliferation, and migration of glioma cells." (PMID 34646821, 2021). "A recent report showed that H19 was elevated in glioma cells and contributed to maintain the stemness properties and malignant behaviors of glioma cells." (PMID 34421359, 2021). "The oncogenic role of H19 has been previously proposed for a wide range of malignancies, including adult high-grade gliomas." (PMID 34502082, 2021). "Increasing evidence had shown that H19 regulated the development of glioma by regulating the Wnt/β-catenin signaling pathway." (PMID 34977037, 2021). "Dual-luciferase reporter analyses showed that H19 was transcriptionally activated by CREB1 in glioma cells after irradiation." (PMID 34159190, 2021). "Theoretically, there are numerous lncRNAs, such as HOTAIR, H19 and NEAT1, that can be applied as diagnostic and prognostic indicators of glioma." (PMID 34178684, 2021). "One recent study demonstrated that H19 promoted glioma cells proliferation, migration, and angiogenesis in vivo." (PMID 34796112, 2021). "Cell cycle and proliferation: Knockdown of H19 inhibited glioma cell growth, indicating that H19 interacts with the cell cycle and enhances glioma proliferation." (PMID 34322395, 2021). "Then, we modified the expression of H19 and observed the changes in the radioresistance of glioma cells." (PMID 34159190, 2021). "Autophagy: H19 overexpression suppressed autophagy of glioma cells via regulating the mammalian target of rapamycin (mTOR)/Unc-51 like autophagy activating kinase 1 (ULK1) axis by inducing increased ULK1 phosphorylation and inhibiting mTOR phosphorylation." (PMID 34322395, 2021). "This study elucidated the mechanism of H19's transcriptional activation after irradiation and identified H19 as a potential target to improve the radiotherapy efficacy of glioma." (PMID 34159190, 2021). "Data of transwell assay indicated that silenced H19 expression reduced the invasive and migratory capacities of glioma cells." (PMID 34796112, 2021). "Because HIF-1α was in turn a target for miR-138, this finding explained why H19 affected angiogenesis, migration as well as proliferation of the glioma cells through targeting HIF-1α and affecting VEGF expression." (PMID 34646821, 2021). "They found that H19 was upregulated in glioma cells and tissues, and was negatively correlated with patient survival." (PMID 34421359, 2021). "The increase of H19 after irradiation indicated that H19 participated in the response of glioma cells to X-rays." (PMID 34159190, 2021). "Further studies showed that high expression levels of H19 in glioma cells, promotes development of glioma and invasive metastasis which is consistent with the findings of our study on genomic instability showing a distinct signature." (PMID 34081618, 2021). "We found that the expression level of lncRNA H19 was elevated by radiation, and then, the modulation of H19 affected the resistant of glioma cells to X-rays." (PMID 34159190, 2021). "As a sponge for miR-675, H19 can regulate the proliferation and migration of glioma cells by producing miR-675 to inhibit the expression of CDK6." (PMID 34692695, 2021).
glioma (continued). "In glioma, when the expression of H19 increases, the expression of miR-152 decreases; consequently, the downregulation of H19 can negatively regulate the expression of miR-152 to inhibit the proliferation and invasion of glioma cells." (PMID 34615480, 2021). "Downregulated H19 also induces cell apoptosis by blocking activation of the Wnt/β-catenin signaling pathway in glioma cells, and it can lead to epithelial–mesenchymal transition (EMT), with reduced N-cadherin and vimentin." (PMID 32650527, 2020). "H19 expression is significantly up-regulated in glioma microvessels and glioma-induced endothelial cells (GECs)." (PMID 32549757, 2020). "The results showed that H19 in GBM was observably higher than that in other types of gliomas, and the expression level of H19 increased with the malignant degree (P <0.01)." (PMID 32081833, 2020). "For example, H19 was described as an oncogene in glioma via inducing angiogenesis through repressing miR-29a19." (PMID 32826866, 2020). "Glioma cells show upregulation of H19, which act as a ceRNA for inhibition of miR-138, leading to activation of VEGF signaling and subsequent glioma angiogenesis." (PMID 35006436, 2020). "Recently, there have been many reports on the expression and functions of IncRNA H19 in cancers, including glioma." (PMID 32081833, 2020). "H19 is specifically upregulated in glioma cell lines and promotes glioma cell growth by targeting mir-140." (PMID 32883200, 2020). "The expression level of H19 in serum-free cultured glioma cells was higher than that in serum cultured ones." (PMID 32081833, 2020). "In the present study, we found that H19 was highly expressed in glioma tissues by Oncomine database analyses." (PMID 32081833, 2020). "Although we explored the relationship between H19 expression and glioma via bioinformatics, this study lacks related validation in vivo and in vitro." (PMID 32081833, 2020). "Univariate analysis of the correlation of H19 expression and immune infiltrates with OS among glioma patients." (PMID 32081833, 2020). "Herein, the expression level of lncRNA H19 in glioma tissues, and its relevance with clinical characteristics were analyzed through Oncomine." (PMID 32081833, 2020). "H19 has been reported to participate in the regulation of a variety of diseases, especially in gliomas." (PMID 32081833, 2020). "Glioma invasion is promoted in a HIF1α-dependent manner through the expression of lncRNAs H19 and AWPPH." (PMID 33126510, 2020). "The results showed that H19 was highly expressed in glioma tissues and its expression increased with the increase of malignancy." (PMID 32081833, 2020). "Since 2001, we have found eight studies involving the differential expression of H19 between glioma and normal tissues in the Oncomine database, with a total of 567 samples." (PMID 32081833, 2020). "First, we analyzed the expression of H19 in glioma tissue, the relationship between H19 and glioma patient's clinical characteristics, and the prognostics value of H19 by Oncomine and GEPIA database." (PMID 32081833, 2020). "Based on Limma and beeswarm package analyses, we discovered that H19 was clearly up-regulated in gliomas." (PMID 32081833, 2020). "Herein, the relationship between the expression level of H19 and glioma was investigated from the perspective of bioinformatics." (PMID 32081833, 2020). "Based on the Oncomine database, we performed a range of correlation analyses between the expression level of H19 and clinical features in glioma patients." (PMID 32081833, 2020). "According to previous studies, lncRNA H19 promoted gliomas progression and angiogenesis by regulating several microRNAs." (PMID 33178271, 2020). "Among them, there were 10 studies about the up-regulation of H19 and one study about its downregulation in Brain and CNS cancers (P <0.01, Gene Rank<Top 10%)." (PMID 32081833, 2020).
glioma (continued). "Among them, there were five studies on the up-regulation of H19 and no studies on its downregulation in Brain and CNS (central nervous system) cancers, which suggested that H19 was up-regulated in brain and CNS cancers." (PMID 32081833, 2020). "Another example is the lncRNA H19, which promotes glioma cell invasion and the epithelial-mesenchymal transition by acting as a ceRNA of miR-67521." (PMID 31358735, 2019). "For instance, VASH2 has been shown promote angiogenesis in tumors and H19 lncRNA—highly expressed in glioma cells—upregulates VASH2 through the H19/miR-29a/ VASH2 axis." (PMID 31404273, 2019). "Knockdown of H19 inhibited glioma-induced endothelial cell proliferation, migration and tube formation in vitro." (PMID 31448238, 2019). "For example, lncRNA H19 expression is markedly induced in glioma and correlates positively with the glioma grade, and its expression is required for tumor invasion and progression." (PMID 31798634, 2019). "Together, these reports strongly suggest and important role for H19 in neovascularization in glioma through at least three lncRNA/miRNA/mRNA axes." (PMID 31404273, 2019). "Two independent studies focused on lncRNA H19 and its involvement in the biology of glioma via the interaction with miRNAs." (PMID 30217088, 2018). "In human glioma, the expression of H19 has been shown to also significantly increase in temozolomide-resistant cells, with silencing of H19 decreasing resistance to temozolomide by inhibition of EMT." (PMID 30619763, 2018). "H19 lncRNA and its derivate miR-675-5p positively correlate with glioma grade and the H19/miR-675 signaling axis has been recently reported to promote glioma cell invasion." (PMID 29963265, 2018). "The presence of several lncRNAs like CRNDE, HOTAIRM1 and H19 among the upregulated transcripts, were in concordance with earlier reports on their oncogenic role in glioma." (PMID 30038703, 2018). "Since H19 was previously reported to serve as a precursor of miR-675-5p and miR-675-3p, the authors looked at the expression levels of these miRNAs in 185 glioma samples from Chinese Glioma Genome Atlas (CGGA)." (PMID 30217088, 2018). "Since it has been recently demonstrated the involvement of the long non-coding RNAs (lncRNAs) in the progression of gliomas, the expression of H19 lncRNA, as well as of one of its two mature products miR-675-5p was evaluated in neurospheres." (PMID 29963265, 2018). "Previously we performed a series of assays that demonstrated H19, which is highly expressed in glioblastomas, promotes glioma cell invasion by inducing miR-675 expression." (PMID 28327666, 2017). "In spite of the critical role of H19 in the maintenance of glioma stemness, its exact mechanism is still unclear and needs to be further investigated." (PMID 28293170, 2017). "We also proved significantly positive correlation of Hif-1α and H19 depending on PTEN status in human GBM, since mutation or loss of expression of PTEN is usual in glioma and occurs in about 40% of GBM24." (PMID 28327666, 2017). "MicroRNA-675 (miR-675-5p), a miRNA in the first exon of H19, is up-regulated in several cancer types, including glioma." (PMID 28187439, 2017). "Several studies have shown that both IGF2-P4 transcripts and H19 are highly expressed in human glioblastoma cell lines and high-grade gliomas, affecting cell growth and motility." (PMID 28187439, 2017). "H19 was significantly upregulated in glioblastomas compared to low grade gliomas in The Cancer Genome Atlas (TCGA)." (PMID 28327666, 2017). "H19 expression and miR-675 level were closely correlated with tumor grade in different glioma data sets." (PMID 26623562, 2016). "In accordance with these results, it was recently shown that H19 promotes glioma cell invasion through miR-675." (PMID 26623562, 2016).